PROM1 (prominin 1)
Description:
May play a role in cell differentiation, proliferation and apoptosis. Binds cholesterol in cholesterol-containing plasma membrane microdomains and may play a role in the organization of the apical plasma membrane in epithelial cells. During early retinal development acts as a key regulator of disk morphogenesis. Involved in regulation of MAPK and Akt signaling pathways. In neuroblastoma cells suppresses cell differentiation such as neurite outgrowth in a RET-dependent manner.
Synonyms: CD133; PROML1; MSTP061; AC133; RP41; CORD12; MCDR2; STGD4
Tractability: Antibody: its Gene Ontology location is reachable by antibodies, with high confidence; UniProt places it where antibodies can reach, with medium confidence; UniProt predicts a signal peptide or a membrane-spanning region; the Human Protein Atlas places it where antibodies can reach. PROTAC: its protein half-life has been measured.
Gene: Protein-coding gene on chromosome 4 (15,963,076 to 16,084,378, reverse strand). Ensembl gene ENSG00000007062.
Subcellular location: Apical cell membrane; Cell projection, microvillus membrane; Cell projection, cilium, photoreceptor outer segment; Endoplasmic reticulum; Endoplasmic reticulum-Golgi intermediate compartment
Subcellular location (Human Protein Atlas): Plasma membrane
Pathways (Reactome):
Developmental Biology: Developmental Lineage of Pancreatic Ductal Cells
Gene Ontology:
Molecular function: actinin binding; cadherin binding; protein binding
Biological process: camera-type eye photoreceptor cell differentiation; glomerular parietal epithelial cell differentiation; photoreceptor cell maintenance; podocyte differentiation; positive regulation of nephron tubule epithelial cell differentiation; retina morphogenesis in camera-type eye; microvillus organization; retina layer formation
Cellular component: cell surface; endoplasmic reticulum; endoplasmic reticulum-Golgi intermediate compartment; extracellular exosome; extracellular region; photoreceptor outer segment membrane; plasma membrane; vesicle; apical plasma membrane; cilium; microvillus; photoreceptor outer segment; prominosome; membrane; microvillus membrane
Genetic constraint (gnomAD): Loss-of-function variants: 87 observed, 94.16 expected, observed/expected ratio (o/e) 0.92, 90% interval 0.78 to 1.1. The upper end of that interval is the gene's LOEUF score, 1.1, which puts it in group 4 of 6, group 1 being the genes least tolerant of losing a copy. Missense variants: 1,025 observed, 938.44 expected, observed/expected ratio (o/e) 1.09, 90% interval 1.04 to 1.15. Synonymous variants: 371 observed, 354.27 expected, observed/expected ratio (o/e) 1.05, 90% interval 0.96 to 1.14.
Gene-disease validity (ClinGen):
ClinGen rates the evidence that PROM1 causes each of these diseases.
PROM1-related dominant retinopathy (autosomal dominant): Definitive. Any retinopathy caused by an autosomal dominant variant in the PROM1 gene.
PROM1-related recessive retinopathy (autosomal recessive): Definitive. Any retinopathy caused by autosomal recessive variants in the PROM1 gene.
Homologues: Orthologues: chimpanzee PROM1 (99% identical), macaque PROM1 (95% identical), rabbit PROM1 (67% identical), dog PROM1 (63% identical), rat Prom1 (62% identical), guinea pig PROM1 (61% identical), mouse Prom1 (61% identical), pig PROM1 (53% identical), tropical clawed frog prom1 (50% identical), zebrafish prom1a (42% identical), zebrafish prom1b (41% identical), Drosophila melanogaster promL (19% identical), and 2 more. Paralogues in human: PROM2 (24% identical).
Diseases named in the same sentence as PROM1 in open-access papers:
PROM1 is named in the same sentence as 468 diseases in open-access papers, as found by Europe PMC text mining. Sharing a sentence is not in itself a finding about the gene and the disease. The quoted sentences say what the papers report.
glioma (726 papers, 2006 to 2026). A benign or malignant brain and spinal cord tumor that arises from glial cells (astrocytes, oligodendrocytes, ependymal cells). "MTAP deficiency leads to epigenetic reprogramming, promotes the formation of glioma stem-like cells, increases PROM1/CD133 expression and tumor incidence, and is associated with poor patient prognosis." (PMID 40761256, 2025). "MTAP loss leads to hypomethylation of PROM1/CD133-related stemness networks to mediate glioma stem-like cell formation, providing a promising therapeutic opportunity for GBM." (PMID 37091983, 2023). "This can be explained by hypermethylation and downregulation of PROM1 that encodes for CD133, the bona fide stem cell marker of glioma." (PMID 33221817, 2020). "Previous studies have also demonstrated that the stem-like features of melanoma cells are associated with the presence of CD133 (also known as prominin-1), which is a glioma and neural stem cell marker." (PMID 26622576, 2015). "In brain cancers, prominin-1 has been shown to highlight cancer stem cells and prominin-1+ glioma cells have been shown to be resistant to radiotherapy." (PMID 39881297, 2025). "Genes linked to stemness and therapy resistance included CD133 (PROM1), SOX2, Nestin, OLIG2, and Musashi-1, all of which support the persistence of glioma stem-like cell populations and drive recurrence." (PMID 41179304, 2025). "The P1, P2 and P3 promoters of PROM1 gene show high proportion of CpG islands and are differentially methylated in normal and cancer tissues such as glioma or colon cancer." (PMID 38532366, 2024). "CD133 or prominin-1, a transmembrane glycoprotein, is used to select highly chemo- and radioresistant glioma cells subset." (PMID 36768445, 2023). "In gliomas, the most commonly used stem cell marker is prominin-1 (CD133), a glycoprotein and neural stem cell marker involved in cellular differentiation and epithelial to mesenchymal transition." (PMID 38275375, 2023). "As expected, ROC‐325 and TMZ exhibited synergistic effect in gliomas, ROC‐325 also inhibited PROM1 expression by blocked TMZ‐induced autophagic flux." (PMID 35882624, 2022). "The correlation between ATG9B and PROM1 expression was also consistent with coimmunostaining of frozen glioma sections." (PMID 35882624, 2022). "Glioma cell cultures and patient-derived glioma cell lines (PDGCLs) expressing Prominin-1 (CD133) were used." (PMID 35312943, 2022). "BMP‐4 reduced the expression of glioma stem cell marker mRNAs, including PROM1, OLIG2, and SOX2, in TGS‐01 as well as in TGS‐04 cells." (PMID 34214250, 2022). "MTAP deficiency leads to increased expression of PROM1/CD133 which results in enhanced tumorigenicity of GBM cells and also promotes glioma stem-like cell (GSC) formation." (PMID 36572880, 2022). "We also assumed that the higher sensitivity of the glioblastoma cells to the VV-GMCSF-Lact action was due to the high number of cells carrying CD133, also known as prominin-1, glioma stem cell markers." (PMID 34685455, 2021). "Bao and coworkers reported that the fraction of tumor cell fractions expressing CD133 (Prominin-1) (a marker of neural stem cells and brain cancer stem cells) were enriched after radiation in gliomas." (PMID 32942996, 2020). "In this method, CD133 or prominin 1, a highly expressing tumor antigen found in glioma, human hepatocellular carcinoma (HCC), in addition to the cancer stem cells (CSCs), was targeted for OVs." (PMID 29473868, 2018). "A transmembrane protein CD133 (also known as prominin-1) is expressed in hematopoietic and neural stem cells (NSCs) and glioma stem-like cells (GSCs)." (PMID 26086074, 2015). "Stem-like features of melanoma cells were additionally associated with the presence of the glioma and neural stem cell marker CD133 (also known as PROM1)." (PMID 24799129, 2014). "CD133 (prominin-1) has been uniformly used to mark glioma stem cells; yet, CD133-negative tumor cells have also been reported to generate tumors under specific conditions." (PMID 25594016, 2014).
glioma (continued). "As in the normal brain, our results suggest a reassessment of the role for PROM1 in CNS cancers beyond that of a highly specific stem cell marker often assumed in this setting." (PMID 25184684, 2014). "The incidence of tumors was 100% for mice implanted either with Prom1+ or Prom1− cells and the induced tumors had characteristics of high-grade gliomas with areas of necrosis and pseudo-palisading and microvascular proliferation." (PMID 23637986, 2013). "The significantly increased vessel density in the tumor clearly indicated that Prom1+ endothelium is capable of incorporating into the proneural glioma vasculature, triggering a higher vasculogenic activity to establish functional tumor vessels." (PMID 23637986, 2013). "This notion is further supported by existence of prominin-1–positive cancer stem cells such as those derived from gliomas." (PMID 23723983, 2013). "For example, the cell-surface protein CD133 (or prominin-1), which is expressed by stem cells of the human brain has also been used to enrich for stem cells in gliomas and has been considered as a marker for cells with enhanced tumorigenicity." (PMID 21483788, 2011). "We confirmed that A20 is highly coexpressed with the glioma stem cell marker CD133 (Prominin-1) when cells were isolated from a patient specimen passaged short term in immunocompromised mice or directly isolated from patient specimens." (PMID 20186265, 2010). "We show here that Prom1 expression is induced in the peripheral cells of tumor-spheres in culture and a portion of glioma in vivo as shown in human GBM." (PMID 19718438, 2009). "Further highlighting PROM1’s complex role, different studies reveal that PROM1’s prognostic significance varies across different cancer types, with its expression and methylation having contrasting implications in gliomas and papillary RCC." (PMID 40650074, 2025). "On the other hand, in glioma cell lines, increasing ECM stiffness causes an increase in BCL9L, a transcriptional coactivator of the β-catenin/TCF complex that favors the gene transcription of its target genes, including PROM1 (gene-coding CD133 protein)." (PMID 37922108, 2024). "High levels of H3K9me2 repressive mark in PROM1 P1 promoter inhibit its activity and CD133 expression in glioma cells, whereas G9a (histone-lysine N-methyltransferase, H3 lysine-9 specific 3) inhibition by bix01294 increases CD133 and Sox2 expression resulting in improved sphere-forming efficiency." (PMID 37922108, 2024). "In our study, we defined glioma stem cells by CD133 (PROM1) or SOX2 protein expression using semiquantative immunohistochemistry, recognizing that additional computational approaches may be more widely available in the near future." (PMID 36333778, 2022). "Thus, the mRNA level of encoding gene PROM1 can be used to differentiate between GBM and low-grade gliomas." (PMID 36040678, 2022). "CD133, also known as prominin-1, is a transmembrane glycoprotein expressed on the surface of neural stem cells in the developing and adult CNS and is a key histological marker for gliomas." (PMID 34394104, 2021). "One of the criteria used to define glioma stem cells is the expression of stem cell markers, including CD133 (prominin-1), sox2, Olig2, nestin, brain lipid binding protein (BLBP), and CD44, which derive from studies on both CNS and non-CNS progenitor cell populations." (PMID 25594016, 2014). "Fluorescence-activated cell sorting (FACS) sorting to enrich for glioma stem cells has relied on the presence of the glycosylated form of the cell surface marker CD133 (Prominin-1): a protein whose role in tumorigenesis and glioma biology remains unclear." (PMID 20186265, 2010). "Moreover, the regulation of glioma cell invasion has been associated with ARF6, which can form a complex with Rac1 and IQGAP1 suggesting a potential link between prominin-1, ARF6 and their interactors in distinct but interconnected processes such as cell migration and EV release." (PMID 39881297, 2025).
glioma (continued). "Furthermore, there were also profound differences in the steady-state levels of several proteins implicated as therapeutic targets in GB such as glioma promoting factor TGFβ, TMZ-resistance factor MGMT, stemness marker CD133/Prominin-1 or the marker of Proneural subtype PDFGRα." (PMID 32102350, 2020). "Further work is needed to determine whether selective targeting of angiocrine factors in brain Prom1+ endothelial cells will block glioma growth in proneural GBM tumors and whether Prom1+ endothelial cells are determinant in sustaining tumor growth in other GBM subclasses." (PMID 23637986, 2013). "Clusters with high entropy were further validated to exhibit the elevated expression of canonical glioma stem-like cell markers (SOX2, OLIG2, PROM1), supporting their classification as high-stemness populations beyond theoretical entropy alone." (PMID 40806540, 2025). "Here we present evidence for the stem cell marker prominin-1 and the chemotherapeutic target ICAM-1 in a glioma animal model and GBM pathology sections from patients that elicited alternative responses to adjuvant chemotherapy." (PMID 38258133, 2024). "These glioma stem cells (GSC) express antigens such as Nestin, CD133 (prominin-1), Musashi-1 and Bmi-1 that are specific to neural stem and progenitor cells." (PMID 35269752, 2022). "Past studies reported that glioma stem-like cells expressing CD133 (Prominin-1, PROM1) can survive ionizing radiation, leading to recurrence." (PMID 34066132, 2021). "CD133 (Prominin-1, PROM1), a well-known marker for both neural stem cells and brain cancer stem cells, has been found to be enriched after radiation in gliomas." (PMID 34066132, 2021). "Glioma CSCs are marked by common stem cell markers, such as CD133, CD15, CD44, Prominin-1, L1CAM and NPM1." (PMID 32725165, 2020). "The most common GSC marker CD133, also known as prominin-1 (PROM1), is used to isolate GSCs by fluorescence-activated cell sorting (FACS) in primary glioma tissues and the cell lines U87 and T98G." (PMID 31653034, 2019). "As cited before, CSCs are identified as CD44+ CD24−/low in breast tumors while, in gliomas, they have been identified mostly on the basis of the expression of CD133 (or prominin 1)." (PMID 23476653, 2013). "As glioma subpopulations expressing Prominin-1 (CD133+) are enriched for CSC, which mark quite specifically brain CSC, we quantified the expression of CD133+ cells in U87MG tumours." (PMID 19293809, 2009). "Here, we identify a population of malignant cells expressing Prominin-1 in a non-proliferating state in pediatric high-grade glioma patients." (PMID 35970913, 2022). "Prominin 1 (PROM1, CD133) is a widely used CSC marker suitable for its isolation from various tumors, including colon, lung, pancreas, and gastric cancers, as well as gliomas and many others." (PMID 36077272, 2022). "Pediatric non-cycling PROM1+ cells were further classified according to the expression of other putative glioma stem cells marker such as SOX2 and OLIG2: 54% expressed both markers, 32% only SOX2, 6% only OLIG2, and 8% neither (right)." (PMID 35970913, 2022). "Additionally, in silico differential analysis of PROM1, SOX2, and NANOG transcript levels was performed on clinical samples from GBM and low-grade glioma (LGG) and compared to healthy tissues as described in the Methods section." (PMID 36497426, 2022). "The differentiated cells diminished expression of nestin, CD133 (prominin-1), and A2B5 putative glioma stem-cell markers, attenuated growth, diminished expression of ligands for activating NK cell receptors, while upregulating class I HLA ligands for NK cell inhibitory receptors." (PMID 29967607, 2018). "Glioma CSCs were initially defined by the expression of the surface marker CD133 (prominin-1), and cells not expressing this marker were thought to lack tumorigenic potential." (PMID 24473088, 2014).
glioma (continued). "We found no increase in glioma initiation by implantation of Prom1+ dissociated cells from Prom1+ over Prom1− tumorsphere cells, suggesting no advantage of Prom1+ cells in the growth of proneural brain tumor enriched in PDGF signaling." (PMID 23637986, 2013). "Interestingly, in gliomas, the TIC population was enriched via cell sorting based on the expression of a single cell surface marker, CD133 (PROM1)." (PMID 22225988, 2012). "The association of prominin-1 with the midbody at the end of cytokinesis in NE cells is not necessarily a general phenomenon, as such inclusion is not observed in dividing CD34+ HSPCs or in glioma cells." (PMID 39881297, 2025). "Interestingly, a thorough analysis of the relationship between promoter hypomethylation and increased CD133 expression in glioma revealed novel transcriptional coregulators of CD133 expression, specificity protein 1 and c-MYC, which can bind only to a hypomethylated PROM1 promoter." (PMID 38532366, 2024). "Similarly, PROM1 is markedly hypermethylated and downregulated only in IDHmut gliomas, not other IDHmut cancers." (PMID 31222125, 2019). "Similarly, CD133 (PROM1), a stem cell marker found particularly enriched in pseudopalisades surrounding necrosis, correlates with tumor growth, therapy resistance, and recurrence in GBM stem cells, with high levels observed in EVs from both melanoma and glioma." (PMID 39594703, 2024). "However, it remains controversial whether Prom1 is a bona fide marker for CSCs as it has been indicated that Prom1-negative glioma cell lines in normoxia become positive for Prom1 in hypoxia, which is one of the characteristics of GBM, and that its expression is reversible upon re-oxygenation." (PMID 19718438, 2009). "LN18 glioma cells grown as non-adherent cells at a low density under serum-free conditions form spheres and display higher expression of stemness markers (NANOG, POU5F1, SOX2 and PROM-1) than adherent LN18 cells." (PMID 33050631, 2020).